HOXB9 (homeobox B9)
Description:
Sequence-specific transcription factor which is part of a developmental regulatory system that provides cells with specific positional identities on the anterior-posterior axis.
Synonyms: HOX2E; HOX-2.5; HOX2
Tractability: PROTAC: UniProt records ubiquitination sites on it.
Gene: Protein-coding gene on chromosome 17 (48,621,156 to 48,626,358, reverse strand). Ensembl gene ENSG00000170689.
Subcellular location: Nucleus
Subcellular location (Human Protein Atlas): Nucleoplasm
Gene Ontology:
Molecular function: protein binding; sequence-specific double-stranded DNA binding; DNA-binding transcription factor activity; DNA-binding transcription factor activity, RNA polymerase II-specific; RNA polymerase II cis-regulatory region sequence-specific DNA binding; DNA binding; RNA polymerase II transcription regulatory region sequence-specific DNA binding
Biological process: cell chemotaxis; anterior/posterior pattern specification; embryonic skeletal system morphogenesis; proximal/distal pattern formation; regulation of transcription by RNA polymerase II; DNA-templated transcription; regulation of DNA-templated transcription
Cellular component: nucleoplasm; chromatin; nucleus; RNA polymerase II transcription regulator complex
Genetic constraint (gnomAD): Loss-of-function variants: 10 observed, 17.63 expected, observed/expected ratio (o/e) 0.57, 90% interval 0.35 to 0.96. The upper end of that interval is the gene's LOEUF score, 0.96, which puts it in group 4 of 6, group 1 being the genes least tolerant of losing a copy. Missense variants: 373 observed, 314.12 expected, observed/expected ratio (o/e) 1.19, 90% interval 1.09 to 1.29. Synonymous variants: 154 observed, 134.44 expected, observed/expected ratio (o/e) 1.15, 90% interval 1 to 1.31.
Homologues: Orthologues: chimpanzee HOXB9 (99% identical), pig HOXB9 (99% identical), dog HOXB9 (99% identical), macaque HOXB9 (99% identical), rabbit HOXB9 (99% identical), mouse Hoxb9 (97% identical), guinea pig HOXB9 (94% identical), zebrafish hoxb9a (73% identical), tropical clawed frog hoxb9 (73% identical), rat Hoxb9 (70% identical). Paralogues in human: HOXD9 (51% identical), HOXC9 (50% identical), HOXA10 (35% identical), HOXD10 (35% identical), HOXC10 (32% identical), HOXC12 (27% identical), HOXA3 (25% identical), HOXA7 (25% identical), HOXC4 (25% identical), HOXD4 (25% identical), HOXB6 (24% identical), HOXB7 (24% identical), and 30 more.
Diseases named in the same sentence as HOXB9 in open-access papers:
HOXB9 is named in the same sentence as 74 diseases in open-access papers, as found by Europe PMC text mining. Sharing a sentence is not in itself a finding about the gene and the disease. The quoted sentences say what the papers report.
lung adenocarcinoma (21 papers, 2015 to 2023). A carcinoma that arises from the lung and is characterized by the presence of malignant glandular epithelial cells. "Increased expression of HOXB9 has been linked to unfavorable survival outcomes in multiple types of cancer, such as adrenocortical carcinoma, lung adenocarcinomas, and breast cancer." (PMID 37301547, 2023). "Intriguingly, a close positive correlation between HOXB9 and GalNAc-T14 was observed both in 31 NSCLC cell lines and in 23 lung adenocarcinoma patients, implying that GalNAc-T14 expression is closely associated with HOXB9 expression in lung cancer." (PMID 26544896, 2015). "Taken together, expression level of GalNAc-T14 and HOXB9 are each associated with the risk of poor overall survival and high recurrence in lung adenocarcinoma patients." (PMID 26544896, 2015). "In a large data set (461 cases for the TCGA), GalNAc-T14 and HOXB9 expression was apparently associated with an increased risk of poor overall survival and high recurrence in lung adenocarcinoma patients, indicating a possible clinical relevance for their involvement in metastasis." (PMID 26544896, 2015). "HOXB9 was also an enabler of multi-organ metastasis of lung adenocarcinoma by activating the WNT/TCF pathway and was also a metastatic promoter of colon cancer and a potential biomarker of bevacizumab therapy." (PMID 37301547, 2023). "PCAF also acetylates transcriptional factor HOXB9, leading to the suppression of lung adenocarcinoma progression via the targeting of oncogenic protein JMJD6." (PMID 36678613, 2023). "LEF1 and HOXB9, two Wnt target genes, are identified as promoters of lung adenocarcinoma metastasis, and WNT/TCF pathway is identified as a determinant of metastasis to bone in lung adenocarcinoma." (PMID 34256750, 2021). "PCAF-mediated acetylation of the transcriptional factor HOXB9 suppresses lung adenocarcinoma progression." (PMID 30833716, 2019). "HOXB9 was found to be overexpressed in lung adenocarcinoma and human breast cancer, whereas in colon adenocarcinoma, pancreatic ductal adenocarcinoma and gastric carcinoma patients, its expression is decreased." (PMID 29724991, 2018). "In the previous study, we found HOXB9-regulated lung adenocarcinoma progression by directly targeting JMJD618." (PMID 29724991, 2018). "We also found HOXB9 regulated lung adenocarcinoma progression by targeting oncogenic protein JMJD618." (PMID 29724991, 2018). "Taken together, we showed evidence that GalNAc-T14 expression is responsible for Wnt/β-catenin-dependent HOXB9 expression, which was critical for increased metastatic potential in lung adenocarcinoma." (PMID 26544896, 2015). "Here, we show that GalNAc-T14 increases β-catenin protein stability and the subsequent Wnt target gene response, particularly the induction of HOXB9, the expression of which is critical for the invasive properties of lung adenocarcinoma." (PMID 26544896, 2015). "In adults, deregulation of HOXB9 expression has been found to be crucial to breast carcinoma and lung adenocarcinoma metastasis." (PMID 26536658, 2015). "We also assessed the prognostic significance of GalNAc-T14 and HOXB9 in patients with lung adenocarcinoma." (PMID 26544896, 2015). "Furthermore, high expression of transcriptional factor HOXB9 predicts poor prognosis in patients with lung adenocarcinoma." (PMID 37301547, 2023). "Although improving the sensitivity and specificity of HOXB9 methylation is recommended, our work provided a preliminary proof of concept on the usefulness of HOXB9 methylation for opening up more clinical options to manage lung adenocarcinoma." (PMID 34036228, 2021). "Furthermore, HOXB9 acetylation at K27 predicts a better prognosis for patients with lung adenocarcinoma." (PMID 33171691, 2020).
lung adenocarcinoma (continued). "In vivo studies in a cohort of 75 lung adenocarcinoma patients showed that people with higher levels of HOXB9 acetylation had significantly better overall survival, smaller tumor size, and lower lymph node metastasis when compared to those with lower levels of HOXB9 acetylation." (PMID 28587176, 2017). "Very recently, a genome-wide DNA methylation analysis revealed that HOXB9 DNA methylation was linked to intrinsic EGFR-TKI resistance and complementary to mutation profiling could discern whether lung adenocarcinoma patients would benefit from EGFR-TKI treatment." (PMID 34885084, 2021). "HOXB9 was also identified as a target gene of WNT/TCF signaling, enhancing the competence of lung adenocarcinoma cells to colonize the bones and brain." (PMID 36674764, 2023). "In lung adenocarcinomas, hyperactive WNT/TCF pathway signaling up regulates HOXB9 and LEF1 expression, which appears to promote brain and bone metastasis." (PMID 26536658, 2015). "Moreover, HOXB9 was also found to be the most significantly increased gene in a microarray database of PC9-BrM3 cells (GSE14107), which are derived from the PC9 lung adenocarcinoma cell line and form brain metastases with close to 100% efficiency." (PMID 26544896, 2015). "Moreover, one study has indicated that Wnt/β-catenin signaling controls metastatic colonization of target organs and that human lung adenocarcinomas enhance the competence of lung adenocarcinoma cells to colonize bone and brain tissues using distinct Wnt signaling pathways through LEF1 and HOXB9." (PMID 28757546, 2017).
breast carcinoma (20 papers, 2014 to 2023). "Since HOXB9 has been implicated in lung metastasis of breast carcinoma, we investigated the role of HOXB9 in PCa tissues." (PMID 34247196, 2021). "In this study, we isolated a homeodomain-less, novel HOXB9 variant (HOXB9v) from human breast cancer cell line-derived mRNA." (PMID 32104178, 2020). "In the present study, we identified and characterized a HOXB9 variant (HOXB9v) of mRNA from human breast cancer cell lines." (PMID 32104178, 2020). "HOXB9 has been shown to be overexpressed in human breast cancer and is associated with tumorigenicity, lung metastasis, and radioresistance." (PMID 24885802, 2014). "HOXB9 is also associated with a worse clinical prognosis in breast cancer patients." (PMID 25136922, 2014). "Moreover, although HOXB9 did not affect the disease free survival after surgery, increased HOXB9 expression in colorectal cancer was significantly associated with a poor prognosis in overall survival, as previously reported for breast cancer." (PMID 24885802, 2014). "In breast cancer, increased HOXB9 was reported to promote the progression and metastasis of the cancer cells." (PMID 36158877, 2022). "In breast cancer, high expression of HOXB9 stimulates the expression of various vascular factors (such as transforming growth factor, TGF-β) that prepares tumor cells for proliferation and metastasis." (PMID 36158877, 2022). "HOXB9, a TF induces angiogenesis, increased cell motility, and acquisition of mesenchymal characters, thus contributing to lung metastasis of breast cancer." (PMID 35095892, 2021). "The induction of HOXB9 expression by E2F1 was observed in several breast cancer cell lines and a significant correlation between E2F1 and HOXB9 was revealed in clinical breast cancer samples indicating their potential role in breast cancer progression." (PMID 33171691, 2020). "The duration of disease-free and overall survival of patients with HOXB9-positive breast cancer is significantly shorter compared with patients with HOXB9-negative breast cancer." (PMID 32104178, 2020). "We next performed PCR analyses to verify the presence of the HOXB9v transcript and identify genomic DNA variations of the HOXB9 gene in human breast cancer cell lines." (PMID 32104178, 2020). "HOXB9 is overexpressed in breast cancer and promotes expression of various tumor growth and angiogenic factors." (PMID 26536658, 2015). "Similar to the reported discrepancy in expression, HOXB9 was found to play oncogenic roles in breast cancer, whereas act as a tumor suppressor in GC." (PMID 26536658, 2015). "While HOXB9 has been extensively investigated in lung and breast carcinomas, its role in gastric carcinomas (GCs) is poorly understood." (PMID 26536658, 2015). "For example, the transcription factor, HOXB9, is overexpressed in breast cancer cells inducing the expression of AR, resulting in increased cell motility." (PMID 25825984, 2015). "The induction of HOXB9 expression by E2F1 was observed by Q-PCR in several breast cancer cell lines overexpressing E2F1." (PMID 25136922, 2014). "HOXB9 overexpression was identified in 43% of breast cancer tissues and strongly correlated with high tumor grade." (PMID 25136922, 2014). "In our previous study, we examined 141 breast cancer tissues for HOXB9 expression by immunohistochemistry." (PMID 25136922, 2014). "Our in vitro analysis identified the TFBS of the HOXB9 promoter region and suggested that E2F1 is a direct regulator of HOXB9 expression; these data support the strong correlation we found between E2F1 and HOXB9 in clinical breast cancer samples." (PMID 25136922, 2014). "HOXB9, a class I homebox gene, is overexpressed in breast cancer and it induces an epithelial-to-mesenchymal transition, a key factor in metastasis." (PMID 24965135, 2014). "High HOXB9 expression in breast cancer was correlated with high tumor grade and poor prognosis." (PMID 28808656, 2017).
breast carcinoma (continued). "In a study on breast cancer, the sensitivity of breast cancer cell lines to killing by HXR9 was shown to be strongly associated with the combined expression of HOX genes HOXB1 through to HOXB9." (PMID 28423659, 2017). "However, the level of HOXB9 expression is lower in gastric tumors, whereas it is upregulated in breast cancer." (PMID 26536658, 2015). "Our findings are in keeping with the observed increase in migration and invasion in breast cancer, where elevated HOXB9 expression enhances the DNA damage response, not only conferring resistance to ionizing radiation, but also associated with induction of epithelial to mesenchymal transition (EMT)." (PMID 25860510, 2015). "Moreover, the transforming growth factor (TGF) -beta axis was regulated by HOXB9 in colorectal cancer, similar to the results previously obtained for breast cancer." (PMID 24885802, 2014). "Moreover, breast cancer cells overexpressing HOXB9 are resistant to ionizing radiation due to an enhanced DNA damage response." (PMID 25136922, 2014). "Further investigation of PD-0332991 as a suppressor of HOXB9 expression in a clinical setting may provide a novel strategy to control breast cancer progression and prolong patients' survival." (PMID 25136922, 2014). "Sunitinib also suppressed cell proliferation in HOXB9-overexpressing breast cancer xenografts." (PMID 24885802, 2014). "The HOXB9 long 5′ flanking region from −2,989 to +246 (the transcription start site was designated as +1) was obtained by PCR amplification of genomic DNA from the human breast cancer cell line MCF7." (PMID 25136922, 2014). "In addition to regulating important developmental functions, HOXB9 has been reported to be elevated in various tumor cells, including colorectal cancer, breast cancer, and hepatocellular carcinoma, wherein increased HOXB9 expression is a predictor of poor outcomes." (PMID 35634239, 2022). "Similar to HOXA10, HOXB9 and HOXC6 also play a physiological role in mammary gland development and are also overexpressed in several tumors, including breast cancer." (PMID 32796699, 2020). "In a study on breast cancer, the sensitivity of breast cancer cell to killing by HXR9 was shown to be strongly related to the expression of HOXB1 through to HOXB9." (PMID 28808656, 2017). "In breast cancer, HOXA5 and HOXB13 expression is down-regulated whereas HOXB9 is highly up-regulated and changes in HOX gene expression have been reported in lung and gastric cancer." (PMID 25860510, 2015). "Homeobox B9 (HOXB9), a member of the homeobox gene family, is overexpressed in breast cancer and promotes tumor progression and metastasis by stimulating epithelial-to-mesenchymal transition and angiogenesis within the tumor microenvironment." (PMID 25136922, 2014). "HOXB9 activates the TGFβ-ATM axis, leading to checkpoint activation and DNA repair, which engenders radioresistance in breast cancer cells." (PMID 25136922, 2014). "In this study, PD-0332991 treatment decreased expression of E2F1 and reduced HOXB9 and its target genes in MCF7 breast carcinoma cells." (PMID 25136922, 2014). "Immunohistochemical analysis of 139 breast cancer tissue samples revealed a significant correlation between E2F1 and HOXB9 expression (p<0.001)." (PMID 25136922, 2014). "Several authors indicate that BPA increases HOXB9 and HOXC6 expression both in cultured human breast cancer cells (MCF7) and in the mammary glands of ovariectomized rats (25 μg/kg), suggesting these transcription factors as mediators of BPA harmful effects in breast tumor." (PMID 32796699, 2020). "By PCR of breast cancer cell lines' genomic DNA, no bands indicative of genomic DNA variations in HOXB9 were detected." (PMID 32104178, 2020). "Thus, to further confirm the presence of HOXB9v in human breast cancer samples, we reanalyzed a publicly available breast cancer RNA sequence data set (GSE119937) and mapped the reads onto the HOXB9 gene sequence." (PMID 32104178, 2020).
breast carcinoma (continued). "The hexapeptide motif is one of the regulatory sites in HOXB9 that interacts with cofactors such as Pbx1 to induce downstream gene expression and promote EMT and other tumorigenic events when it is aberrantly expressed such as that observed in breast cancers." (PMID 26536658, 2015). "The comparison between HOXB9-positive and -negative tumors of breast cancer patients revealed a considerable difference in disease-free and overall survival rate." (PMID 25136922, 2014). "HOXB9 has been reported to be overexpressed in neoplastic tissues; to promote the expression of angiogenic factors, ErbB, and TGF-beta ligands; and to promote angiogenesis and distant metastasis in breast cancer." (PMID 24885802, 2014). "Despite detailed reports of the role of HOXB9 in breast cancer, the factors that regulate HOXB9 transcription have not been extensively examined." (PMID 25136922, 2014). "In this cohort, more than half of HR(+)/HER2(−) and breast cancer tissues were negative for both HOXB9 and E2F1." (PMID 25136922, 2014). "We thus investigated whether PD-0332991 also inhibits E2F1 expression in BT-549 breast cancer cells, which has high expression of endogenous HOXB9 and E2F1, compare to the control (MCF7 cells), and whether this treatment would affect HOXB9 expression." (PMID 25136922, 2014). "More than half of HR(+)/HER2(−) breast cancer tissues were negative for both HOXB9 and E2F1." (PMID 25136922, 2014).